ENSG00000277572
Gene: Miscellaneous RNA gene on chromosome 21 (14,075,950 to 14,076,038, reverse strand). Ensembl gene ENSG00000277572.
Gene Ontology:
Biological process: chromatin remodeling